BRCA1 (BRCA1 DNA repair associated)
Diseases named in the same sentence as BRCA1 in open-access papers (continued):
Sharing a sentence is not in itself a finding about the gene and the disease.
ovarian carcinoma (continued). "First, the same set of genes that distinguished BRCA1 and BRCA2-associated tumors also segregated the sporadic (not BRCA1 or BRCA2-associated) ovarian cancers into 2 subgroups consisting of "BRCA1-like" and "BRCA2-like" gene expression profiles." (PMID 15383145, 2004). "Among the 478 ovarian cancer patients, 19 BRCA1 mutations were identified (4.0%), and no mutation was discovered among the 190 patients with borderline tumours." (PMID 15477862, 2004). "No somatic BRCA1 gene mutations have been identified without simultaneous germline mutations, unlike ovarian cancer, where single somatic BRCA1-truncating mutations have been identified." (PMID 12698194, 2003). "The BRCA1 gene and its protein products have been the subject of intensive investigation over recent years because of their proven role in hereditary and putative role in sporadic human breast and ovarian cancer." (PMID 12698194, 2003). "The corresponding ovarian cancer risks were 25.9% for BRCA1 and 9.1% for BRCA2." (PMID 11857015, 2002). "The corresponding ovarian cancer risks were 32.8% for BRCA1 and 17.8% for BRCA2." (PMID 11857015, 2002). "Women who have inherited a mutation in the BRCA1 or BRCA2 gene have approximately an 80% risk of developing breast cancer over their lifetime, particularly at a young age, and a 40–60% lifetime risk of ovarian cancer." (PMID 11857010, 2002). "Mutations in BRCA1 and BRCA2 both confer greatly elevated risks for ovarian cancer." (PMID 11875732, 2002). "Germline mutations in BRCA1 and BRCA2 genes predispose to hereditary breast and ovarian cancer." (PMID 11237395, 2001). "The dominantly inherited ovarian cancer predisposing genes, BRCA1, BRCA2 and genes involved in the hereditary non-polyposis colorectal cancer (HNPCC) syndrome, have recently been identified." (PMID 9652774, 1998). "We identified a novel BRCA1 mutation in two Jewish-non-Ashkenazi families with ovarian cancer: a thymidine to guanidine alteration at position 3053, resulting in substitution of tyrosine at codon 1017 for a stop codon (Tyr1017Ter)." (PMID 9667663, 1998). "Furthermore, women with genetic mutations in the BRCA1- and BRCA2-associated hereditary breast and ovarian cancer (HBOC) syndrome at risk of developing breast and ovarian cancer opt for oocyte cryopreservation prior to a prophylactic oophorectomy at an early age." (PMID 41528507, 2026). "In BRCA1/2 mutant ovarian cancer cells that depend on PARP-mediated single-strand repair due to homologous recombination repair (HR) deficiency caused by BRCA gene mutations, a subset of these cells may acquire secondary reversion mutations in the BRCA1/2 genes." (PMID 41219748, 2025). "However, the potential risk of malignant cell reintroduction upon ovarian tissue transplantation is a significant concern in BRCA1/2 patients who may develop occult ovarian cancer." (PMID 40142718, 2025). "One of the most discussed uses of PGT from an ethical point of view is hereditary breast and ovarian cancer syndrome (HBOC) in which the risk is induced by carrying BRCA1/2 mutations which increase the risk for breast and ovarian cancer but not before 30 years of age and usually much later." (PMID 39940681, 2025). "Additionally, we did not account for the risk of synchronous breast and ovarian cancers in BRCA1/2 carriers." (PMID 40567951, 2025). "A multicenter case–control study (n = 360) demonstrated that 76.7% of ovarian cancer patients and BRCA1 mutation carriers exhibited a non-Lactobacillus-dominated (Type O) vaginal microbiota, contrasting with the Lactobacillus-dominated (Type L) communities prevalent in healthy controls (p < 0.05)." (PMID 40732683, 2025).
ovarian carcinoma (continued). "If patients with ovarian cancer have a hereditary burden of cancer and do not have a BRCA1/2 mutation, they may undergo broad-panel, commercially available, next-generation genetic sequencing (NGS) testing." (PMID 40429755, 2025). "The detection of BRCA1/2 mutations is routinely used as a strong predictor of response to PARP inhibitors, while HER2, TROP2, and FOLR1 expressions have emerged as primary targets for the treatment of recurrent ovarian cancer patients using novel antibody–drug conjugates (ADCs)." (PMID 40507303, 2025). "For instance, sRNAs derived from Fusobacterium nucleatum may suppress the transcription of tumor suppressor genes such as BRCA1 while promoting the epigenetic activation of pro-inflammatory genes like IL-6, thereby accelerating the progression of ovarian cancer." (PMID 40732683, 2025). "Interestingly, genomic variation in the miR-191 sequence has been suggested to predispose to familial ovarian cancer in patients without the BRCA1/2 or MMR gene mutation background." (PMID 41008855, 2025). "Guidelines from the American Society of Clinical Oncology (ASCO) and the National Comprehensive Cancer Network (NCCN) recommend all women diagnosed with epithelial ovarian cancer undergo germline genetic testing for BRCA1 and BRCA2 and other susceptible genes, regardless of their family history." (PMID 40894326, 2025). "Moreover, the Spanish Society of Medical Oncology clinical guidelines for ovarian cancer indicate that PARPis induce cell death in HRRD-positive tumor cells through a “synthetic lethality” mechanism, with BRCA1 and BRCA2 mutations being one of the established causes of HRRD in tumors." (PMID 41223417, 2025). "Finally, recent research has highlighted the potential significance of molecular biomarkers such as BRCA1/2, homologous recombination status (HR status), microsatellite instability (MSI), mismatch repair (MMR), and tumor mutational burden (TMB) in ovarian cancer." (PMID 39878156, 2025). "However, oral contraceptives should not be used to reduce ovarian cancer risk in BRCA1/2-pV carriers or pV-carriers in other risk genes for breast and ovarian cancer." (PMID 39259360, 2024). "Oral contraceptives should not be used to reduce ovarian cancer risk in BRCA1/2-pV carriers." (PMID 39259360, 2024). "Moreover, STIC lesions can be found in women without a genetic predisposition to ovarian cancer at similar rates to women with BRCA1/2 mutations, suggesting that sporadic cases of ovarian cancer likewise originate in the FT." (PMID 38271085, 2024). "However, unlike breast and ovarian carcinomas, “non-canonical” malignancies arising in BRCA1/2 mutation carriers relatively rarely involve inactivation of the remaining gene allele." (PMID 38612902, 2024). "In addition to BRCA1 and BRCA2 mutations, it is crucial to recognize that various other genetic mutations, such as those in RAD51C, ATM, and CHEK2, can induce HR deficiency in ovarian cancer." (PMID 38391958, 2024). "In our study, germline deleterious mutations in RECQL4 were significantly associated with a family history in patients without BRCA1/2 mutations, suggesting that it may be also related to ovarian cancer susceptibility." (PMID 38509102, 2024). "Additionally, recent studies suggest that BRCA1/BRCA2, well-known tumor suppressor genes frequently mutated in hereditary breast and ovarian cancers, may play a role in autophagy regulation." (PMID 39199310, 2024). "However, several clinical trials have shown that the accuracy of these genes in predicting the response to PARPis is similar to that of BRCA1/2 in patients with recurrent ovarian cancer and even lessened when olaparib is combined with bevacizumab in newly diagnosed patients." (PMID 38374229, 2024).
ovarian carcinoma (continued). "PARPi agents have been approved to treat ovarian cancer patients with and without BRCA1/2 mutations and/or other HR deficiencies, and combined treatment with the PARPi olaparib and the VEGFA-selective blocker bevacizumab is FDA-approved for ovarian cancer as maintenance therapy." (PMID 38956205, 2024). "Data from The Cancer Genome Atlas (TCGA) revealed that RAD18 mRNA is more highly expressed in BRCA1-mutated breast tumors, relative to BRCA2-mutated and WT tumors (left), although RAD18 mRNA expression does not appear to be significantly enriched in BRCA1-mutated ovarian carcinomas (right)." (PMID 38943334, 2024). "We then utilized a curated human ovarian cancer Tissue Microarray (TMA), containing WT, BRCA1-mutated, and BRCA2-mutated ovarian serous carcinoma sections to test whether the RAD18-dependent fork recovery pathway is upregulated in BRCA1 mutant tumors by immunohistochemical (IHC) analysis." (PMID 38943334, 2024). "While loss of BRCA1 promoter methylation during therapy has been described in ovarian cancer, notably, such loss of methylation may not explain therapy resistance in the TNT trial since methylation status was determined in samples collected at trial inclusion." (PMID 40225940, 2024). "Thus, BRCA1/2 mutations, which are generally observed in only 22% of ovarian cancer patients do not unmask all HRD cases." (PMID 39077473, 2024). "Similarly, BRCA1 had been considered a candidate oncogene and has been found to be highly expressed in several other types of tumors, such as digestive system cancers, ovarian cancer, lung adenocarcinoma." (PMID 38224491, 2024). "BRCA reversion mutations, frequently involving deletions of <100 bp, restore the open reading frame of BRCA1/2 and can be detected in circulating cell-free DNA, providing a minimally invasive method to monitor treatment effectiveness and guide further interventions in ovarian cancer." (PMID 38396858, 2024). "Moreover, the following studies focused on implementing the breast and ovarian cancer SNP313 PRS for BRCA1/2 carriers, to evaluate how its application may influence cancer risk guidance for women with pathogenic variants in these genes." (PMID 38397209, 2024). "Similarly, for ovarian cancer (OC), the risk of development in healthy individuals is estimated to be 1–2%, while in BRCA2-positive individuals, it increases to 39–44%, with a greater impact for BRCA1 variants (11–17%)." (PMID 38792636, 2024). "This shift value, in our understanding, represents the difference in the time of cancer occurrence; therefore, this means that patients with BRCA1/BRCA2 mutations are diagnosed with breast or ovary cancer approximately two years earlier than patients without such mutations." (PMID 38279352, 2024). "The cytotoxic potential of arsenite was evaluated after treatment with NaAsO2 in the presence or absence of IR on UWB1.289 (BRCA1-null ovarian cancer cell line; BRCA1-deficient) and UWB1.289 + BRCA1 (BRCA1-wild-type, BRCA1-proficient) cells to define appropriate incubation conditions." (PMID 37762697, 2023). "These genetic alterations might consist of epistatic effects, multiple combinations of mutations, unlike the simple mutations present in BRCA1/2 that cause ovarian cancer." (PMID 36981032, 2023). "Moreover, family members will not gain access to cascade testing and breast/ovarian cancer risk-reduction strategies in related, unaffected germline BRCA1/2 heterozygotes." (PMID 38201604, 2023). "There is growing evidence that PARP inhibitors are equally efficacious in ovarian cancers without BRCA1/2 mutations, which may be caused by other molecular defects." (PMID 37206208, 2023). "Only one patient with non-high-grade ovarian cancer had a tumour BRCA1/2 pathogenic variant." (PMID 38201604, 2023).
ovarian carcinoma (continued). "Epithelial ovarian cancer patients with BRCA1/2 mutations exhibit a superior response to platinum-based chemotherapies compared with those without BRCA1/2 mutations, resulting in improved survival rates, despite the disease being diagnosed at an advanced stage and higher grade." (PMID 37621847, 2023). "Comparing BRCA1/2-mutation carriers with women who are not at high risk for breast or ovarian cancer, may have provided a stronger significance in our results." (PMID 37393265, 2023). "Previous findings have suggested that the distribution of ovarian cancer histopathology subtypes differs in germline BRCA1 and BRCA2 pathogenic variant carriers, compared to non-carriers, with a similar distribution associated with pathogenic variants for the two genes." (PMID 37076566, 2023). "The cancer risks and spectra appear to differ between BRCA1 and BRCA2 carriers; specifically, the risk for ovarian cancer in BRCA1 carriers is higher than BRCA2 carriers, and the risks for pancreatic and prostate cancers in BRCA2 carriers may be higher than BRCA1 carriers." (PMID 36861435, 2023). "For decades, hereditary breast and ovarian cancer (HBOC) has been attributed to PVs in the genes BRCA1 and BRCA2, and more recently other rare alleles have been firmly established as associated with a high or moderate increased risk of developing breast and/or ovarian cancer." (PMID 37563628, 2023). "Additionally, before 70 years of age, ovarian cancer may manifest in 39% of females with detrimental BRCA1 alteration and 11%–17% of females with BRCA2 alteration." (PMID 36971312, 2023). "Also, while the distinction in sensitivity between BRCA1 and BRCA2-associated ovarian cancers remains unclear in the clinical setting, emerging in vitro data does indicate that all BRCA mutations are not equal in their functionality." (PMID 37415740, 2023). "Most missense substitutions in BRCA1 are variants of unknown significance (VUS), and individuals with a VUS in BRCA1 cannot know from genetic information alone whether this variant predisposes to breast or ovarian cancer." (PMID 37578980, 2023). "Germline monoallelic pathogenic BRCA1 mutations are known to be associated with hereditary breast/ovarian cancer, however biallelic mutations of BRCA1 were long predicted to be incompatible with embryonic viability, hence BRCA1 was not considered to be a canonical FA gene." (PMID 38146508, 2023). "Two BRCA1 variants, previously not described in the Slovenian population, are c.3331_3334delCAAG and c.4065_4068delTCAA, which have been identified in other populations in breast and ovarian cancer patients." (PMID 37002323, 2023). "Thus, BRCA1 gene status screening is vital for breast and ovarian cancer prevention strategies." (PMID 36614323, 2023). "Consistently, a retrospective case-control analysis of ovarian cancer patients enrolled in the ARIEL2 and ARIEL3 trials suggested an increased incidence of tMN among patients carrying pathogenic variants in genes involved in homologous recombination pathway (BRCA1, BRCA2, RAD51C and RAD51D)." (PMID 37119509, 2023). "Over the past thirty years, genetic testing for inherited pathogenic variants in the BRCA1 and BRCA2 genes in patients with suspected hereditary breast and ovarian cancer (HBOC) has moved from research to being an established part of breast and ovarian cancer care." (PMID 37563628, 2023). "However, recent studies have revealed that increased DDX39B could promote the tumour metastasis of colorectal cancer and enhance chemotherapy resistance in BRCA1-proficient ovarian cancers." (PMID 35141281, 2022). "Thus, disruption of SFXN4 enhances the efficacy of platinum-based compounds and PARP inhibitors in a variety of ovarian cancer cell lines, including some with no known functional mutations in BRCA1/2 (A2780Cis, MDAH2774)." (PMID 36402786, 2022).
ovarian carcinoma (continued). "The genes that were most frequently reported in recent subgroup MINAS reports, after BRCA1 and BRCA2, included CHEK2, ATM and FANCM, which would be consistent with these ‘newer’ breast CSGs increasingly being included in gene testing panels for breast/ovarian cancer susceptibility." (PMID 34983940, 2022). "One clinical study showed that in patients with platinum-resistant BRCA1/2 mutation ovarian cancer, olaparib as maintenance monotherapy showed a progression-free survival (PFS) of 11.2 months compared to 4.3 months with placebo, a dramatic improvement for treating ovarian cancer patients." (PMID 35165509, 2022). "However, our department is also a referral center for the treatment of ovarian cancer, therefore a large number of BRCA1/2 mutation carriers (affected and non-affected) perform the breast screening program at our institute." (PMID 36230495, 2022). "The results suggest that BRCA1 deficiency may cause inadequate DNA damage repair due to the lack of DNA damage repair factors in ovarian cancer cells." (PMID 35517499, 2022). "Furthermore, platinum sensitivity correlated with lower BRCA1/2 mRNA expression in ovarian cancers." (PMID 35203410, 2022). "Accordingly, we observed that disruption of SFXN4 decreases DNA repair in vitro and in vivo and increases the efficacy of platinum-based compounds and PARP inhibitors in a variety of ovarian cancer cell lines, including some with no known functional mutations in BRCA1/2 (A2780Cis, MDAH2774." (PMID 36402786, 2022). "However, taking into account the current diagnostic standards of patients with ovarian cancer in the context of determining the optimal treatment and qualifying patients for treatment with PARP inhibitors, the BRCA1/2 gene is routinely tested using the NGS method in DNA extracted from tumour cells." (PMID 35382848, 2022). "In addition, it is well known that some HRR genes such as BRCA1/2, ATM, BRAD1, BRIP1, PALB2, RAD51C, and RAD51D are associated with high risk of ovarian cancers, and tissue detection might be a good way to learn the germline status." (PMID 35186721, 2022). "Furthermore, the location of their mutation is not variable as with BRCA1/2, which determines the risk of ovarian cancer." (PMID 35805770, 2022). "Although BRCA1-Δ11q alternative splice isoform has been shown to contribute to cisplatin-resistance in ovarian cancer, the alternative splicing rate or BRCA1-Δ11q level was not altered by frameshift mutations in exon 11-induced NMD or its containing-transcripts." (PMID 37223641, 2022). "Thus, BRCA1/2 sequencing is more and more commonly ordered by oncologists as a test performed on tDNA not only for patients with ovarian cancer but also for specific patients with prostate cancer and pancreatic cancer in whom such therapy could be considered." (PMID 36171877, 2022). "Similarly, BRCA1/2 germline variants are prevalent among these subtypes; however, in our study populations, BRCA1/2 carriers were more common among those with an additional ovarian cancer whereas NCBP1 carriers more frequently had an additional cervical cancer." (PMID 36199081, 2022). "Next, we compared the survival status of ovarian cancer patients with or without BRCA1 deficiency." (PMID 35517499, 2022). "In addition, when we simultaneously treated the BRCA1 knock-down ovarian cancer cells with dobutamine and the ADRB1-specific antagonist atenolol, the levels of cAMP decreased to the basal level, whereas the ADRB2-specific antagonist ICI-118551 had no inhibitory effect." (PMID 35517499, 2022). "Therefore, our novel findings suggest that Cur and PTX combination may be a promising strategy for ovarian cancer treatment, and targeting miR-9-5p/BRCA1 axis may help to improve therapeutic outcomes." (PMID 36703740, 2022).